AHNAK2 (AHNAK nucleoprotein 2)
Synonyms: C14orf78
Tractability: Antibody: its Gene Ontology location is reachable by antibodies, with high confidence; the Human Protein Atlas places it where antibodies can reach. PROTAC: UniProt records ubiquitination sites on it; ubiquitination databases record sites on it.
Gene: Protein-coding gene on chromosome 14 (104,937,244 to 104,978,374, reverse strand). Ensembl gene ENSG00000185567.
Subcellular location: Nucleus
Subcellular location (Human Protein Atlas): Cytosol; Plasma membrane
Gene Ontology:
Molecular function: protein binding
Biological process: regulation of RNA splicing
Cellular component: cytosol; plasma membrane; cytoplasm; nucleus; sarcolemma; T-tubule
Genetic constraint (gnomAD): Loss-of-function variants: 18 observed, 29.1 expected, observed/expected ratio (o/e) 0.62, 90% interval 0.43 to 0.92. The synonymous counts are far from expectation, so gnomAD's model fits this gene poorly and the ratio says little. Missense variants: 8,604 observed, 7,223.7 expected, observed/expected ratio (o/e) 1.19, 90% interval 1.17 to 1.21. Synonymous variants: 3,590 observed, 2,931.6 expected, observed/expected ratio (o/e) 1.22, 90% interval 1.19 to 1.26.
Homologues: Orthologues: chimpanzee AHNAK2 (83% identical), macaque AHNAK2 (81% identical), rat Ahnak2 (51% identical), mouse Ahnak2 (36% identical), Caenorhabditis elegans T19B10.5 (2% identical). Paralogues in human: AHNAK (14% identical), PRX (6% identical).
Diseases named in the same sentence as AHNAK2 in open-access papers:
AHNAK2 is named in the same sentence as 72 diseases in open-access papers, as found by Europe PMC text mining. Sharing a sentence is not in itself a finding about the gene and the disease. The quoted sentences say what the papers report.
lung adenocarcinoma (12 papers, 2020 to 2026). A carcinoma that arises from the lung and is characterized by the presence of malignant glandular epithelial cells. "Over the last seven years, overexpression of AHNAK2 has been reported to be associated with poor prognosis in clear cell renal cell carcinoma, pancreatic ductal adenocarcinoma, uveal melanoma, papillary thyroid carcinoma, and lung adenocarcinoma." (PMID 33918555, 2021). "Moreover, we found that overexpression of AHNAK2 was significantly associated with poor prognosis in lung adenocarcinoma." (PMID 32904605, 2020). "AHNAK2 is over-expressed in several types of cancer, including clear cell renal cell carcinoma, pancreatic ductal adenocarcinoma, uveal melanoma, papillary thyroid carcinoma, and lung adenocarcinoma, where its high expression levels have been linked to poor patient prognosis." (PMID 38166029, 2024). "AHNAK2, CAVIN1, and ODR4 have all been linked to metastatic processes in lung adenocarcinomas or non–small cell lung cancer, pointing to a potential overlap in functionality for homing or microenvironment adaptations." (PMID 41543394, 2026). "While the role of AHNAK in lung adenocarcinoma remains controversial, several studies have now confirmed the role of AHNAK2 as a pro-cancer factor in lung cancer." (PMID 38033502, 2023). "AHNAK2 has been shown to be a prognostic marker in papillary thyroid cancer, clear cell renal cell carcinoma (ccRCC), and lung adenocarcinoma." (PMID 37377953, 2023). "It is worth proposing that AHNAK2 was significantly associated with all four indicators including OS, PFS, DFS and DSS in lung adenocarcinoma patients, which is also consistent with our previous findings." (PMID 38033502, 2023). "The aberrant overexpression of AHNAK2 has been consistently recognized to promote the progression of lung adenocarcinoma, thyroid cancer, and bladder cancer (with at least three reports for each type)." (PMID 38033502, 2023). "AHNAK2 has a strong link with oncogenesis in pancreatic ductal adenocarcinoma, clear cell renal carcinoma, lung adenocarcinoma, gastric cancer, bladder cancer, and uveal melanoma." (PMID 35158796, 2022). "Through the analysis of the public database, the oncogenic role of AHNAK2 in lung adenocarcinoma was also found." (PMID 36017889, 2022). "In agreement with our data, AHNAK2 was upregulated in tumor samples and correlated with poor prognosis in lung adenocarcinoma patients." (PMID 35847888, 2022). "Analyses based on clinical specimens showed that AHNAK2 regulated the EMT via a TGF-β/Smad3 pathway in lung adenocarcinoma and a hypoxia inducible factor-1α/zinc finger E-box-binding homeobox 1 (HIF-1/ZEB1) pathway in clear cell renal cell carcinoma." (PMID 33918555, 2021). "We also collected several datasets and further verified the relationship between AHNAK2 and lung adenocarcinoma." (PMID 32904605, 2020). "The analysis revealed that AHNAK2 was expressed at higher levels in several malignancies compared to normal tissues, including lung adenocarcinoma, kidney renal papillary cell carcinoma, head and neck squamous cell carcinoma, kidney renal clear cell carcinoma, and PAAD." (PMID 41465903, 2025). "It was reported that AHNAK2 expression was upregulated in lung adenocarcinoma and correlated with poor prognosis, which may be an independent factor in determining prognosis." (PMID 38033502, 2023). "Clinicopathological grade correlation with AHNAK2 expression was performed on the TCGA and GEPIA database of lung adenocarcinoma patients, showing a significant positive correlation between high AHNAK2 expression and lymph node metastasis, staging, and poor survival." (PMID 35158796, 2022). "There is an increased expression of AHNAK2 in lung adenocarcinoma vs. pericancerous tissue." (PMID 35158796, 2022). "Furthermore, Gene Ontology (GO) analysis and Kyoto Encyclopedia of Genes and Genomes (KEGG) analysis were used to explore the functional role of AHNAK2 in lung adenocarcinoma." (PMID 32904605, 2020).
lung adenocarcinoma (continued). "Our findings showed that AHNAK2 could be a novel prognostic marker and therapeutic target of lung adenocarcinoma." (PMID 32904605, 2020). "In addition, the migration of lung adenocarcinoma A549 cells was inhibited by AHNAK2 knockdown." (PMID 38033502, 2023). "It was also reported that downregulation of AHNAK2 expression inhibited the phosphorylation of ERK, which inactivated the MAPK signaling pathway and led to the proliferation and migration of lung adenocarcinoma cells." (PMID 38033502, 2023). "In fact, these potential relations between AHNAK2 and the MAPK/ERK and PI3K/AKT pathways were reported in lung adenocarcinoma and uveal melanoma." (PMID 33918555, 2021). "Moreover, AHNAK2 could be an independent prognosis factor for lung adenocarcinoma." (PMID 32904605, 2020). "However, the specific role of AHNAK2 in lung adenocarcinoma remains unknown." (PMID 32904605, 2020). "In addition, using datasets from Broad Institute Cancer Cell Line Encyclopedia (CCLE) lung adenocarcinoma cell lines and TCGA-LUAD, we explored the relation functions and pathways with AHNAK2 in ADC." (PMID 32904605, 2020). "GSEA and KEGG enrichment analysis of lung adenocarcinoma datasets showed a correlation between genes involved in focal adhesion, human papillomavirus infection, the PI3K-AKT signalling pathway, the regulation of actin cytoskeleton, and ECM receptor interactions with AHNAK2." (PMID 35158796, 2022). "Inclusion of Smad3 phosphorylation inhibitors in lung adenocarcinoma cells did not affect the regulation of cell migration, invasion and EMT by TGF-β1 with or without knockdown of AHNAK2, suggesting that AHNAK2 promotes lung adenocarcinoma progression through the TGF-β1/Smad3 pathway." (PMID 38033502, 2023).
pancreatic cancer (11 papers, 2016 to 2025). "Here we explored the role of AHNAK2 in pancreatic cancer, as well as determining its potential utility as a biomarker for PDAC." (PMID 39849106, 2025). "AHNAK2 showed high variability in mRNA expression as well as protein level and distribution in a range of pancreatic cancer cell lines." (PMID 39849106, 2025). "AHNAK2, normally described as a nucleoprotein, was found in the cytoplasm in almost all pancreatic cancer cell lines." (PMID 39849106, 2025). "In gene panels developed for early diagnosis of pancreatic cancer, high AHNAK2 mRNA expression was one possible biomarker." (PMID 39849106, 2025). "AHNAK2 mRNA expression was found to be raised in seven standard pancreatic cancer cell lines (AsPC-1, BxPC-3, Capan-2, CFPAC-1, HPAF-II, PANC-1, and SW 1990) (p < 0.005) in comparison to an immortalised non-tumorigenic pancreatic epithelial cell line (HPDE-6)." (PMID 35158796, 2022). "In pancreatic cancer, the meta-analysis or artificial neural network (ANN) analysis of transcriptome data revealed that AHNAK2 is a diagnostic and prognostic factor." (PMID 36017889, 2022). "AHNAK2 gene was upregulated in pancreatic cancer but the molecular function of this protein is inconclusive." (PMID 35578244, 2022). "An overview of the TMA scores shows that TFF1, LAMC2 and AHNAK2 can be detected in pancreatic cancer samples with a score > 0 in 92, 93, and 53% of all samples, respectively, whereas at least one of the markers was detectable with a score > 0 in 99% of the samples." (PMID 29675033, 2018). "Similarly, AHNAK2, ARL4C, ASAP2 were all highly expressed in pancreatic cancers, correlated with KRAS G12D mutation and could predict survival in pancreatic cancers." (PMID 35785187, 2022). "The results showed that only three feature genes—ANO1, AHNAK2, and ADAM9, were significantly associated with prognosis in all three analyses (p < 0.05), which means that these three feature genes may act as molecular markers for predicting the prognosis of pancreatic cancer patients." (PMID 37170188, 2023). "ANO1, AHNAK2, and ADAM9 were eventually identified as feature genes of pancreatic cancer, helping to diagnose and predict prognosis." (PMID 37170188, 2023). "AHNAK2, ARL4C, ASAP2, SEMA3C were identified as being highly expressed in both KRAS G12D cell lines and pancreatic cancer patients." (PMID 35785187, 2022). "For AHNAK2, it has not been well studied in glioma, but it has been proved to be candidate cancer biomarker in pancreatic cancer and papillary thyroid carcinoma." (PMID 35496054, 2022).
thyroid cancer (10 papers, 2020 to 2025). "Additional functional analysis has shown that AHNAK2 is closely associated with immune cell infiltration and may contribute to thyroid cancer progression by regulating cell adhesion, cell junctions and immune-related pathways." (PMID 38033502, 2023). "Recent research has underscored AHNAK2 as a prognostic marker for cancers such as thyroid cancer, melanoma, PDAC, and bladder cancer." (PMID 40308776, 2025). "Compared with AHNAK, AHNAK2 in thyroid cancer has been relatively well studied and been considered to influence thyroid cancer progression as a pro-carcinogenic factor." (PMID 38033502, 2023). "In the analysis of genomic and epigenomic aberrations, AHNAK2 was revealed to be an oncogene of thyroid cancer, and the analysis of TCGA database further showed that AHNAK2 is a biomarker for the diagnosis and prognosis of thyroid cancer." (PMID 36017889, 2022). "AHNAK2 knockdown was previously reported to activate the Wnt pathway and correlated with tumor immune cell infiltration thyroid cancer." (PMID 36091120, 2022). "AHNAK2 upregulated and promoted tumor progression in multiple cancers, such as melanoma, renal clear cell carcinoma, thyroid cancer, and pancreatic ductal carcinoma." (PMID 32904605, 2020). "It was also found that AHNAK2 may achieve regulation of thyroid cancer migration, invasion and lymph node metastasis through the NF-κB signaling pathway." (PMID 38033502, 2023). "AHNAK2 may promote thyroid cancer progression through cell adhesion-, cell junction-, and immune-related pathways." (PMID 32966238, 2020). "Whilst in PDAC cell lines there was no change in proliferation, in uveal melanoma (UM) and Thyroid Cancer (TC) AHNAK2 upregulates the PI3K/AKT pathway, known to regulate mTOR and thereby controlling proliferation, growth and survival." (PMID 39849106, 2025). "In thyroid cancer, some scholars have shown that the NF-κB pathway, PI3K/AKT signaling pathway, and Wnt/β-catenin pathway may partially explain the unfavorable prognosis in the high expression cohort of AHNAK2." (PMID 39593730, 2024).
bladder cancer (9 papers, 2020 to 2025). "A large sample analysis using the TCGA and GEO databases has been reported to confirm that AHNAK2 is overexpressed in bladder cancer and is associated with poorer overall survival." (PMID 38033502, 2023). "In this validation cohort, the overall mutation frequency of AHNAK2 was 14% with melanoma (17.2%) ranking the most prevalent cancer type followed by non-small cell lung cancer (12.5%) and bladder cancer (7.4%)." (PMID 35359393, 2022). "AHNAK2 is highly expressed in various cancer types, including LUAD, papillary thyroid cancer, and bladder cancer, and is associated with poor prognosis." (PMID 39593730, 2024). "collected pathological specimens from 120 patients who underwent radical resection for bladder cancer for IHC analysis and divided the cases into two groups of high and low AHNAK2 expression based on staining." (PMID 38033502, 2023). "As for bladder cancer, AHNAK2 overexpression predicted poor overall survival and tumor malignancy; the knockdown of AHNAK2 significantly weakened the invasive capacities of bladder tumor cells." (PMID 36091120, 2022). "Mean AHNAK2 levels were higher in bladder cancer patients 49.08 pg/mL (standard deviation = 114.91) compared to controls 5.28 pg/mL (standard deviation = 6.65), P < .05)." (PMID 36416332, 2022). "A potential role for AHNAK2 exists as a urinary, tissue, and blood biomarker in bladder cancer." (PMID 35158796, 2022). "Apart from the molecular biology of AHNAK2 in disease, it would be important to see if AHNAK2 is detectable in patients’ bodily fluids, for possible use as a urinary biomarker in bladder cancer, including serum and plasma as possible predictive, diagnostic, or prognostic biomarkers." (PMID 35158796, 2022). "This study aimed to measure the AHNAK2 urinary levels in bladder cancer patients." (PMID 36416332, 2022). "Data regarding expression levels of AHNAK2 in bladder cancer (BCa) have been very scarce." (PMID 33918555, 2021). "AHNAK2 has been described as a diagnostic biomarker in PDAC, thymic carcinoma, and bladder cancer." (PMID 32966238, 2020). "AHNAK2 protein could be used as bladder cancer surveillance biomarker." (PMID 36416332, 2022). "In recent years, many studies have reported that AHNAK2 could be a biomarker for the diagnosis and prognosis of PDAC, ccRCC, thymic carcinogenesis, bladder cancer, gastric cancer, and UM." (PMID 32966238, 2020). "AHNAK2 was recently reported as a biomarker for the diagnosis and prognosis of pancreatic ductal adenocarcinoma (PDAC), clear cell renal cell carcinoma (ccRCC), thymic carcinoma, bladder cancer, gastric cancer, and uveal melanoma (UM)." (PMID 32966238, 2020).
breast carcinoma (9 papers, 2019 to 2025). "In functional studies,AHNAK2 knockdown significantly inhibited the progression and metastasis of breast cancer and cervical cancer." (PMID 36017889, 2022). "We also examined the expression pattern of AHNAK2 using breast cancer, colorectal cancer, and esophageal adenocarcinomas tissue microarrays." (PMID 36017889, 2022). "Our study revealed that AHNAK2 is highly expressed in a large number of adenocarcinoma tissues, including cervical adenocarcinoma, breast cancer and colorectal cancer, compared with their normal tissue glandular epithelium." (PMID 36017889, 2022). "In addition, AHNAK2 is highly expressed in glandular tissues, which include both cervical cancer and breast cancer." (PMID 41471728, 2025). "Our research provides a clue that AHNAK2 may determine the occurrence and progression of cervical adenocarcinoma and breast cancer by regulating DNA replication." (PMID 36017889, 2022). "AHNAK2 has a reported association with cisplatin (CIS) and 5-fluorouracil (5-FU) resistance, with 5-FU being used in colon, oesophageal, gastric, pancreatic, and breast cancers through the inhibition of thymidylate synthase (TS) and incorporating its metabolites into RNA and DNA." (PMID 35158796, 2022). "In breast carcinoma, epitopes with the highest potential were derived from proteins expressed by BRCA2 and AHNAK2." (PMID 41471728, 2025).
clear cell renal cell carcinoma (9 papers, 2017 to 2024). "Of all cancers, AHNAK2 has been most studied in depth in the context of clear cell renal cell carcinoma (ccRCC)." (PMID 35158796, 2022). "For instance, AHNAK2 expression was identified as upregulated in clear cell renal cell carcinoma based on the comparison between cancer and adjacent normal tissues, leading to further exploration of its prognostic relevance." (PMID 28894185, 2017). "In addition, through the data mining analysis of multiple databases and the verification of key genes in clinical samples (n=355) and cell lines, AHNAK2 was identified as a prognostic marker and oncoprotein of clear cell renal cell carcinoma." (PMID 36017889, 2022). "Moreover, in hypoxic environment, HIF-1α (hypoxia inducible factor-1α) induces the upregulation of AHNAK2 levels and promotes the progression of renal clear cell carcinoma by promoting epithelial-mesenchymal transition (EMT)." (PMID 32904605, 2020). "Previous studies showed AHNAK2 could promote tumor progression and cell migration in melanoma and renal clear cell carcinoma." (PMID 32904605, 2020). "Among these genes we observed CLIC3, PRAP1 and AHNAK2, which have been shown to promote cancer progression of gallbladder carcinoma, chemotherapeutic drug resistance in colorectal cancer and epithelial to mesenchymal transition in clear cell renal cell carcinoma, respectively." (PMID 30717152, 2019). "AHNAK2 belongs to the AHNAK family and was reported to act as an oncogene in papillary thyroid carcinoma, pancreatic ductal adenocarcinoma, and clear cell renal cell carcinoma." (PMID 35251577, 2022).
uveal melanoma (9 papers, 2020 to 2025). A melanoma derived from melanocytes of the uveal tract. "High AHNAK2 expression is linked to shortened patient survival and metastasis in uveal melanoma data (n = 63) from the Gene Expression Omnibus database (GEO)." (PMID 35158796, 2022). "No histological results were available in the reports on the role of AHNAK2 in squamous cell carcinoma, including uveal melanoma and esophageal squamous cell carcinoma." (PMID 36017889, 2022). "AHNAK2 was found to facilitate invasion and migration in uveal melanoma and LUAD." (PMID 35251577, 2022).